COLEC12 (collectin subfamily member 12)
Diseases named in the same sentence as COLEC12 in open-access papers:
COLEC12 is named in the same sentence as 48 diseases in open-access papers, as found by Europe PMC text mining. Sharing a sentence is not in itself a finding about the gene and the disease. The quoted sentences say what the papers report.
osteosarcoma (6 papers, 2020 to 2025). A usually aggressive malignant bone-forming mesenchymal neoplasm, predominantly affecting adolescents and young adults. "As for COLEC12, it was increased in osteosarcoma and remarkably associated with poor survival outcomes, while there are few relevant studies in HCC and further research is needed." (PMID 34627241, 2021). "Our results showed the inhibition of osteosarcoma development caused by COLEC12 knockdown through reducing tumor volume and weight, weakening tumor proliferation, migration, and invasion, and enhancing apoptosis." (PMID 32822099, 2020). "COLEC12 has been shown to regulate apoptosis and inflammatory responses in osteosarcoma, and it promotes enhanced migration and invasion in gastric cancer cells." (PMID 40427030, 2025). "With respect to ZNF532 and COLEC12 in the model, elevated expression of COLEC12 had a worse prognostic outcome and increased inflammation in osteosarcoma." (PMID 37144239, 2023). "COLEC12 is involved in leukocyte recruitment and cancer metastasis and regulates the apoptosis of osteosarcoma." (PMID 35982973, 2022). "In our study, we used GEPIA and TCGA systems to predict COLEC12’s correlation in sarcoma to osteosarcoma." (PMID 32822099, 2020). "The COLEC12 expression and mRNA level in an osteosarcoma tumor were increased (P < .05), compared with para‐carcinoma tissue." (PMID 32822099, 2020). "Then, in order to further investigate the function of COLEC12 in the development of osteosarcoma, we used COLEC12 knockdown lentivirus to reduce COLEC12 expression." (PMID 32822099, 2020). "Our findings indicate that COLEC12 knockdown significantly activates inflammation function and inhibits the development of osteosarcoma modulating through TLR4, and then improve the level of osteosarcoma apoptosis, prolonging the lives of mice." (PMID 32822099, 2020). "Our findings indicate that COLEC12 is possibly able to regulate inflammation in osteosarcoma when mediated through TLR4." (PMID 32822099, 2020). "In this study, we focused on the role of COLEC12 in osteosarcoma and COLEC12 knockdown lentivirus to boost inflammatory progress and tumor development, in vivo and in vitro." (PMID 32822099, 2020). "To eliminate whether TLR4 is involved in the COLEC12 inflammatory function of osteosarcoma, we used TLR4 knockdown lentivirus to block TLR4 expression, which was the preliminary component of inflammation." (PMID 32822099, 2020). "As COLEC12 knockdown administration could regulate osteosarcoma development in vitro, we also detected this progress in vivo." (PMID 32822099, 2020). "COLEC12 knockdown lentivirus could inhibit osteosarcoma development, in vivo and vitro, through reducing tumor volume and weight, weakening tumor proliferation, migration, and invasion, and enhancing apoptosis." (PMID 32822099, 2020). "We found the COLEC12 expression and mRNA level in tumor or Saos‐2 cells were increased which suggested COLEC12 may be related to the development of osteosarcoma." (PMID 32822099, 2020). "The potential mechanisms of inflammation by COLEC12 mediated through TLR4 in osteosarcoma." (PMID 32822099, 2020). "The occurrence and development of osteosarcoma were observed by using COLEC12 knockdown lentivirus." (PMID 32822099, 2020). "Furthermore, COLEC12 knockdown could increase inflammation of osteosarcoma, in vivo and in vitro, through inducing myeloperoxidase (MPO), TLR4, NF‐κB, and C3, and expression of related inflammatory factors." (PMID 32822099, 2020). "It has also been found that increased levels of COLEC12 expression were seen in cancer‐associated stromal cells, which suggests that there is a correlation with tumor inflammation; however, the mechanism of COLEC12 in inflammation of osteosarcoma has not been fully clarified." (PMID 32822099, 2020). "COLEC12 may be able to regulate apoptosis and inflammation of osteosarcoma, and TLR4 may be the downstream target factor of COLEC12 in inflammation." (PMID 32822099, 2020).
osteosarcoma (continued). "However, it has not yet been reported whether the role of COLEC12 for inflammation in osteosarcoma is regulated by TLR4." (PMID 32822099, 2020). "However, whether the role of COLEC12 for inflammation in osteosarcoma is regulated by TLR4 has not been reported." (PMID 32822099, 2020). "However, the mechanism of COLEC12 in inflammation of osteosarcoma is not fully clarified." (PMID 32822099, 2020).
gastric cancer (5 papers, 2018 to 2025). A primary or metastatic malignant neoplasm involving the stomach. "The gene COLEC12 produces a receptor that mediates the cross-talk between dendritic cells and gastric stromal cells and has been associated with the development of gastric cancer patients when deregulated." (PMID 33195511, 2020). "In contrast to gastric mucosa epithelial cell line GES-1, transcriptional levels of PAPPA2, MPO, MAGEA11, DEPP1, CPZ, and COLEC12 were higher in gastric cancer cell lines HGC-27, MKN-28 and AGS, with lower transcriptional level of CYTL1." (PMID 37124627, 2023). "Higher levels of PAPPA2, MPO, MAGEA11, DEPP1, CPZ, and COLEC12 and lower level of CYTL1 were proven in gastric cancer cells versus controls." (PMID 37124627, 2023). "This study experimentally verified the levels of DNA repair-relevant genes, with higher levels of PAPPA2, MPO, MAGEA11, DEPP1, CPZ, and COLEC12 and lower level of CYTL1 in gastric cancer cells versus controls." (PMID 37124627, 2023). "By immunofluorescence, the expression of COLEC12 was clearly evident in GSCs with scattered expression pattern, in stromal cells or its adjacent normal GSC of subjects with gastric cancer." (PMID 29491476, 2018).
anaplastic thyroid cancer (3 papers, 2022 to 2023). "Moreover, COLEC12 is a potential biomarker of anaplastic thyroid cancer (ATC)." (PMID 35982973, 2022). "Another study found that PTX3, Collectin Subfamily Member 12 (COLEC12) and Platelet Derived Growth Factor receptor alfa (PDGFRA) could be used as biomarkers to differentiate the anaplastic thyroid carcinoma from follicular or papillary thyroid carcinomas." (PMID 37025408, 2023).
colon adenocarcinoma (3 papers, 2022 to 2024). "Moreover, COLEC12 as a cancer stemness-related signature could predict colon adenocarcinoma prognosis." (PMID 37144239, 2023).
diabetic retinopathy (3 papers, 2017 to 2023). "Common polymorphisms in or near COLEC12 have been linked to diabetic retinopathy in Chinese patients with T2DM." (PMID 36131924, 2022). "It is interesting, however, that mutations in COLEC12, collectin subfamily member 12 (CLP1), have been associated with profound alterations in brain development and diabetic retinopathy." (PMID 29190776, 2017).
Alzheimer disease (2 papers, 2017 to 2022). A progressive, neurodegenerative disease characterized by loss of function and death of nerve cells in several areas of the brain leading to loss of cognitive function such as memory and language. "Thus, we speculate that COLEC12 may contribute to susceptibility to MetS because MetS is in turn associated with lipid metabolism and Alzheimer’s disease." (PMID 29212154, 2017). "It has also been proposed that the COLEC12 gene is involved in the clearance of amyloid beta, suggesting its contribution to Alzheimer’s disease." (PMID 29212154, 2017). "Importantly, a genome-wide association analysis searching for loci associated with CoQ10 serum levels identified COLEC12 and NRXN-1, which have also been associated with neuropsychiatric disorders, including Alzheimer's Disease, ASD and Schizophrenia." (PMID 35308885, 2022).
depression (2 papers, 2024 to 2025). "IL-1R2, MATN2 and COLEC12 were associated with cardiorespiratory symptoms, fatigue and anxiety/depression; MATN2, CSF3 and C1QA were elevated in gastrointestinal symptoms and C1QA was elevated in cognitive impairment." (PMID 38589621, 2024). "COLEC12's role in immune responses connects it to neuroinflammation and mental health issues, including depression and self-harm." (PMID 40125487, 2025). "COLEC12 and markers of endothelial and mucosal inflammation (MATN2, PCDH1, ROBO1, ISM1, ANGPTL2, TGF-α and TFF2) were highly correlated within the cardioresp, fatigue and anxiety/depression groups." (PMID 38589621, 2024).
gastric diseases (2 papers, 2018 to 2023). "COLEC12 can integrate H. pylori infection, PGE2-EP2/4 pathway as well as innate immunity in gastric diseases." (PMID 37124627, 2023).
glioma (2 papers, 2015 to 2025). A benign or malignant brain and spinal cord tumor that arises from glial cells (astrocytes, oligodendrocytes, ependymal cells). "In comparison to the grade III sample, ECM-affiliated genes (COLEC12, SDC2 and SEMA5A) showed enhanced spatial expression in GBM regions with perivascular microgliosis associated with pseudopalisading necrosis, that are largely absent in lower-grade gliomas." (PMID 41366031, 2025).
colon cancer (1 paper, 2017). "No report was available for the COLEC12 transcript, whereas PRKAA2 was shown to promote colon cancer." (PMID 28962550, 2017).
diabetes (1 paper, 2022). "We provide insights into analyzing immune microenvironments and gene regulation features, indicating that both CPEB1 and COLEC12 are promising targets for immunotherapy of patients with diabetes who are diagnosed with BC." (PMID 36131924, 2022). "In-depth studies of the expression of CPEB1 and COLEC12 in fibroblasts and their roles in immune microenvironment interactions, particularly the complicated mechanisms connecting fibroblasts with immune cells, might provide novel strategies for BC immunotherapies in patients with diabetes." (PMID 36131924, 2022).
E. coli infection (1 paper, 2023). "Further qRT-PCR assays showed that representative genes of phagosome maturation were significantly upregulated in response to E. coli infection including ATP6V1A, ATP6V1B2, BF2, CTSS, and TFRC, while COLEC12 was downregulated at 72 h." (PMID 36411420, 2023).
esophageal cancer (1 paper, 2024). A primary or metastatic malignant neoplasm involving the esophagus. "Genes causally associated with the occurrence of esophageal cancer are identified within the AGG cluster, including CTSZ, CTSC, DAD, COLEC12, ATOX1, etc., offering new evidence for clinical immune therapy." (PMID 38434988, 2024). "Among them, the genes CTSZ, CTSC, DAD, COLEC12, ATOX1, etc., in the TUBA1B+Mac-C0 cluster have a causal relationship with esophageal cancer." (PMID 38434988, 2024). "Mendelian randomization analysis revealed a causal relationship between genes such as CTSZ, CTSC, DAD, COLEC12, ATOX1, within the AGG cluster, and the onset of esophageal cancer." (PMID 38434988, 2024). "The Mendelian randomization results indicate a causal relationship between genes such as CTSZ, CTSC, DAD1, COLEC12, ATOX1 in the TUBA1B+Mac-C0 cluster and the occurrence of esophageal cancer." (PMID 38434988, 2024).
hepatocellular carcinoma (1 paper, 2023). A malignant tumor that arises from hepatocytes. "COLEC12 acts as an innate immune-related risk mRNA that is related to immunosuppression in hepatocellular carcinoma (HCC)." (PMID 37426414, 2023).
Insulin resistance (1 paper, 2019). Increased resistance towards insulin, that is, diminished effectiveness of insulin in reducing blood glucose levels.
multiple sclerosis (1 paper, 2021). A progressive autoimmune disorder affecting the central nervous system resulting in demyelination. "Previous studies on mouse and human macrophages showed that COLEC12 is a novel receptor involved in myelin uptake by phagocytes and may play a role in active multiple sclerosis, which is a chronic, inflammatory, neurodegenerative disease." (PMID 34680941, 2021).
periodontitis (1 paper, 2024). An acute or chronic inflammatory process that affects the tissues that surround and support the teeth. "Comparing the Average global expression profile of neutrophils from healthy PDL versus neutrophils from PDL with periodontitis revealed increased expression of genes such as Il1b, Il1rn, Cebpb, Colec12, Ptgs2, Zfp36, Egr1, Atf3, Csf1, and Lars2 in periodontitis." (PMID 39588378, 2024).
psoriasis (1 paper, 2019). An autoimmune condition characterized by red, well-delineated plaques with silvery scales that are usually on the extensor surfaces and scalp. "Reduction of the scavenger receptor COLEC12 could trigger psoriasis by trastuzumab treatment." (PMID 31388062, 2019).
rheumatoid arthritis (1 paper, 2025). A chronic, systemic autoimmune disorder characterized by inflammation in the synovial membranes and articular surfaces. "Research indicated that COLEC12 was established as an effective rheumatoid arthritis diagnostic marker, and was highly positively correlated with T cells follicular helper infiltration and highly negatively correlated with the expression of mast cells." (PMID 40236664, 2025).
viral infection (1 paper, 2023). "However, no clear studies have yet confirmed this role in the context of viral infection, except one study showing no binding of the SARS-CoV-2 spike to COLEC12, while it did bind other related humoral pattern recognition molecules." (PMID 38140653, 2023).
cancer (10 papers, 2017 to 2025). A tumor composed of atypical neoplastic, often pleomorphic cells that invade other tissues. "COLEC12 is suggested to be involved in leukocyte recruitment and cancer metastasis, and the increasing levels of COLEC12 expression were seen in cancer‐associated stromal cells, which suggests a correlation with tumor inflammation." (PMID 32822099, 2020). "It was also found that increased cytosolic levels of COLEC12 expression were seen in cancer-associated stromal cells, but the reason for this is, at present, unclear." (PMID 29491476, 2018). "Machine learning identified five potential diagnostic biomarkers (COLEC12, TMCC1, CEP55, KLK3, COL4A1) with an AUC of 0.903, which are implicated in immune modulation and cancer progression." (PMID 40427030, 2025). "The shared mRNAs between T2DM and BC were enriched in cytochrome (CYP) pathways, and further analysis of CPEB1 and COLEC12 expression in cell lines, single cells and other cancers showed that they were strongly correlated with the survival and prognosis of patients with BC." (PMID 36131924, 2022). "It works as a pattern recognition molecule that can act as a transmembrane receptor or may lead to opsonophagocytosis in its soluble form.Significantly, COLEC12 binds sialyl Lewis X which interacts with E-selectin during extravasation of leukocytes and cancer cells." (PMID 28994702, 2017).
tumor (7 papers, 2015 to 2025). "In the risk model, CAF abundances in tumor microenvironment were positively connected with the risk score and the levels of ZNF532 and COLEC12." (PMID 37144239, 2023). "In our work, CPEB1 and COLEC12 were expressed at high levels in fibroblast-3 cells, contributing to the construction of the tumor immune microenvironment." (PMID 36131924, 2022). "Results showed COLEC12 expression in SARC tumor tissue was higher than normal; high expression of COLEC12 in SARC patients had a worse prognostic outcome." (PMID 32822099, 2020). "COLEC12 expression in SARC tumor tissue was higher than in normal, and a high expression of COLEC12 in SARC patients had a worse prognostic outcome." (PMID 32822099, 2020). "As COLEC12 expression in the tumor was increased, probably correlated with tumor progression, we attempted a method for decreasing the COLEC12 level: COLEC12 knockdown lentivirus in vitro." (PMID 32822099, 2020). "In conclusion, higher infiltration of stromal CAFs in tumor microenvironment was associated with poor prognosis in CRC, and ZNF532 and COLEC12 could be as novel prognostic CAF biomarkers by producing the prediction model." (PMID 37144239, 2023). "Furthermore, ZNF532 was mainly distributed in cluster 6, and COLEC12 was mainly distributed in cluster 5, which that suggested cluster 6 and cluster 5 in fibroblasts were mainly involved in tumor progression and immunotherapy of CRC." (PMID 37144239, 2023). "Overall, the predictive model composed of ZNF532 and COLEC12 may predict the state of CAF infiltrations in tumor microenvironment." (PMID 37144239, 2023). "Notably, both CPEB1 and COLEC12 were expressed at significantly higher levels in fibroblasts, an essential component of the tumor microenvironment." (PMID 36131924, 2022). "To further confirm whether the tumor‐regulated effect of COLEC12 is mediated through inflammation, we also observed inflammation‐related proteins by Western blot and immunofluorescence." (PMID 32822099, 2020). "The COLEC12 expression and mRNA level in the tumor or Saos‐2 cells were increased." (PMID 32822099, 2020). "The tumor weight in sh‐COLEC12 mice was also reduced (P < .05)." (PMID 32822099, 2020). "These scores all increased in high-expression group of COLEC12, TREM1 and S100A9, while the corresponding tumor purity decreased, which further confirmed the roles of these IRGs in regulating tumor microenvironment." (PMID 36685822, 2022). "COLEC12 could reduce TLR4 expression, weaken NF‐κB and C3 signaling pathway to release inflammatory factors downstream, restrain immune defense to tumor cells, inhibit apoptosis of tumor cells, and cut down lives of mouses." (PMID 32822099, 2020). "In addition, ZNF532 was distributed in endothelial cells, while COLEC12 also belonged to macrophage, speculating CAF signature affecting tumor progression by regulating tumor matrix formation and immune infiltration of CRC." (PMID 37144239, 2023). "Moreover, PTX3, COLEC12 and PDGFRA genes were found as possible candidates for biomarkers of ATC while GPR110 could be tested to distinguish PTC over other tumor subtypes." (PMID 25887408, 2015).
infection (3 papers, 2015 to 2025). The state of being infected such as from the introduction of a foreign agent such as serum, vaccine, antigenic substance or organism. "However, COL14A1, COLEC11, and COLEC12 were uniquely downregulated following Delta infection at 24 hpi." (PMID 41200555, 2025). "Collectin (COLEC12), which acts as opsonin and enhances phagocytosis, was also up-regulated, as well as the avian-specific avidin (AVN), over-expressed both in spleen and skin samples, and whose induction has been shown to occur in response to infection, tissue injury, or inflammation." (PMID 26331304, 2015).
peripheral neuropathy (1 paper, 2024). A disorder affecting the peripheral nervous system. "Through MR analysis, we identified eight proteins (UBC12, SEM4C, IL_23_R, prothrombin, CBS, Microglobulin, MATN4, and COLEC12) with causal relationships to peripheral neuropathy." (PMID 39268072, 2024).
COLEC12 also shares sentences with these, for which no sentence is quoted: astrocytoma (2 papers); bacterial infection (2); metabolic syndrome (2); ameloblastoma (1); Anxiety (1); asthma (1); breast carcinoma (1); Cognitive impairment (1); cryptococcosis (1); ependymoma (1); fungal infection (1); glomerulosclerosis (1); invasive breast carcinoma (1); lung carcinoma (1); melanoma (1); neurodegenerative disease (1); papillary thyroid carcinomas (1); postherpetic neuralgia (1); rectal adenocarcinoma (1); rectal tumor (1); renal cell carcinoma (1); sarcoma (1); schizophrenia (1); thyroid carcinoma (1).